NDUFV2 (NADH:ubiquinone oxidoreductase core subunit V2)
Description:
Core subunit of the mitochondrial membrane respiratory chain NADH dehydrogenase (Complex I) which catalyzes electron transfer from NADH through the respiratory chain, using ubiquinone as an electron acceptor (Probable). Parts of the peripheral arm of the enzyme, where the electrons from NADH are accepted by flavin mononucleotide (FMN) and then passed along a chain of iron-sulfur clusters by electron tunnelling to the final acceptor ubiquinone (Probable). Contains one iron-sulfur cluster (Probable).
Synonyms: CI-24k; MC1DN7
Tractability: Small molecule: an approved drug acts on it; a structure with a bound ligand is known. Antibody: UniProt places it where antibodies can reach, with medium confidence. PROTAC: ubiquitination databases record sites on it; its protein half-life has been measured.
Target class: Enzyme; Oxidoreductase
Gene: Protein-coding gene on chromosome 18 (9,102,433 to 9,134,346, forward strand). Ensembl gene ENSG00000178127.
Subcellular location: Mitochondrion inner membrane
Subcellular location (Human Protein Atlas): Mitochondria; Cytosol; Nucleoplasm
Pathways (Reactome):
Metabolism: Complex I biogenesis; Respiratory electron transport
Gene Ontology:
Molecular function: NADH dehydrogenase (ubiquinone) activity; protein binding; electron transfer activity; NADH dehydrogenase activity; oxidoreductase activity
Biological process: cardiac muscle tissue development; mitochondrial electron transport, NADH to ubiquinone; nervous system development; aerobic respiration; proton motive force-driven mitochondrial ATP synthesis; proton transmembrane transport
Cellular component: mitochondrial inner membrane; mitochondrion; respiratory chain complex I
Genetic constraint (gnomAD): Loss-of-function variants: 7 observed, 21.75 expected, observed/expected ratio (o/e) 0.32, 90% interval 0.18 to 0.6. The upper end of that interval is the gene's LOEUF score, 0.6, which puts it in group 2 of 6, group 1 being the genes least tolerant of losing a copy. Missense variants: 270 observed, 261.37 expected, observed/expected ratio (o/e) 1.03, 90% interval 0.93 to 1.14. Synonymous variants: 78 observed, 85.29 expected, observed/expected ratio (o/e) 0.91, 90% interval 0.76 to 1.1.
Gene-disease validity (ClinGen):
ClinGen rates the evidence that NDUFV2 causes each of these diseases.
mitochondrial disease (autosomal recessive): Definitive.
Leigh syndrome (autosomal recessive): Limited. A progressive neurological disease defined by specific neuropathological features associating brainstem and basal ganglia lesions.
Homologues: Orthologues: rabbit NDUFV2 (97% identical), pig NDUFV2 (96% identical), dog NDUFV2 (96% identical), guinea pig NDUFV2 (94% identical), mouse Ndufv2 (92% identical), rat Ndufv2 (87% identical), tropical clawed frog ndufv2 (80% identical), zebrafish ndufv2 (78% identical), Drosophila melanogaster ND-24 (63% identical), Caenorhabditis elegans nduv-2 (61% identical).
Diseases named in the same sentence as NDUFV2 in open-access papers:
NDUFV2 is named in the same sentence as 43 diseases in open-access papers, as found by Europe PMC text mining. Sharing a sentence is not in itself a finding about the gene and the disease. The quoted sentences say what the papers report.
schizophrenia (16 papers, 2007 to 2023). A major psychotic disorder characterized by abnormalities in the perception or expression of reality. "Of note, mutations in NDUFV2 have been shown to be responsible for schizophrenia, bipolar disorder, Alzheimer’s and Parkinson׳s disease as well as early-onset hypertrophic cardiomyopathy and encephalopathy." (PMID 36768419, 2023). "NDUFV2, encoding a subunit of the inner mitochondrial enzyme complex I, has been linked to bipolar disorder, major depression, schizophrenia and Parkinson’s disease." (PMID 30655508, 2019). "In this study, we genotyped two promoter variants (rs6506640 and rs1156044) of the NDUFV2 gene in a case-control cohort to assess their effect on schizophrenia susceptibility in Han Chinese." (PMID 21190551, 2010). "The NADH-ubiquinone oxidoreductase flavoprotein gene (NDUFV2), which encodes a 24 kD mitochondrial complex I subunit, has been reported to be positively associated with schizophrenia and bipolar disorder in different populations." (PMID 21190551, 2010). "Recent association studies further indicated that the NDUFV2 promoter haplotype, which was constituted by two SNPs (rs6506640-rs1156044), was significantly associated with schizophrenia in Japanese population." (PMID 21190551, 2010). "For example, two single nucleotide polymorphisms (SNPs) in a nuclear encoded subunit of complex I, NDUFV2, were found to be associated with schizophrenia and with bipolar disorder." (PMID 18989376, 2008). "Furthermore, the NDUFV2 gene is associated with psychiatric disorders such as schizophrenia and bipolar disorder." (PMID 29358944, 2017). "This phenotype may explain why the deficiency of NDUFV2 subunit has been associated with some neurodegenerative diseases, including Parkinson disease, Alzheimer's disease, Bipolar disorder, and Schizophrenia." (PMID 21548921, 2011). "Specifically, mRNA levels of Ubiquinone Oxidoreductase Core Subunit V1 (NDUFV1), NDUFA8, NDUFB9, NDUFS4, NDUFS7, and NDUFV2 were decreased in the frontal cortex of patients with schizophrenia compared with controls." (PMID 37107350, 2023). "Lower protein levels of complex I subunits encoding genes NDUFV2 and NDUFS1 were identified in various brain regions of patients affected by Down syndrome or Morbus Alzheimer’s and schizophrenia." (PMID 37508386, 2023). "The mitochondrial-related proteins (ATP5H, SSBP1, SLC25A4 and NDUFV2) previously shown to be differentially expressed in the PSD in schizophrenia were also differentially expressed in the PSD in bipolar disorder." (PMID 27898073, 2016). "We observed marginally significant associations with schizophrenia of rs10908826, rs4656994, rs5085 and rs2307424 in the NDUFS2 gene and rs12457810, rs12964485 and rs2377961 in the NDUFV2 gene." (PMID 26053550, 2015). "NDUFV2 is a subunit of the mitochondrial respiratory chain and its protein expression levels are reduced in the frontal cortex and striatum in schizophrenia." (PMID 22567321, 2011). "More studies with large sample size and population from different regions, as well as, functional assays should be conducted to finally elucidate the role of NDUFV2 in schizophrenia." (PMID 21190551, 2010). "The role of NDUFV2 played in schizophrenia needs to be further studied." (PMID 21190551, 2010). "Subsequent analyses showed a decreased level of NDUFV2 expression in postmortem prefrontal cortex and striatum of schizophrenia patients and in lymphoblastoid cell line of Caucasian schizophrenia patients, suggesting an active involvement of NDUFV2 in schizophrenia." (PMID 21190551, 2010). "In order to further study whether Sp1 plays a role in the regulation of genes abnormally expressed in schizophrenia, we chose the NDUFV2 subunit of complex I, which was the most substantially affected in schizophrenia in both brain and periphery." (PMID 17786189, 2007).
schizophrenia (continued). "Moreover, the TATA-less 5′-flanking sequence of the human NDUFV2, which was the most affected subunit of complex I in schizophrenia, demonstrated a promoter activity." (PMID 17786189, 2007). "In contrast, the mRNA expression of NDUFB2, NDUFB5, and NDUFS4 was decreased in the hippocampus and the mRNAs of NDUFV1, NDUFV2, and NADUFS1 in the striatum of patients with schizophrenia." (PMID 37107350, 2023). "The mRNA level of NDUFV1, NDUFV2, and NDUFS1 in the first-episode schizophrenia patients was higher than that in the controls, and the mRNA level of NDUFV2 was higher in the chronic schizophrenia patients than in the controls." (PMID 25713723, 2014). "The mRNA level of NDUFV2 was positively correlated with BPRS and SAPS scores in the first-episode schizophrenia subgroup." (PMID 25713723, 2014). "The level of mRNA expression of NDUFV1, NDUFV2, and NDUFS1 was significantly higher in the schizophrenia group than in the control group." (PMID 25713723, 2014). "There was a significant difference in the mRNA level of NDUFV1 (P = 0.003), NDUFV2 (P < 0.01), and NDUFS1 (P = 0.003) between the first-episode schizophrenia patients and control subjects." (PMID 25713723, 2014). "Previously, we have reported schizophrenia and tissue specific alterations in the expression of complex I subunits, NDUFV1 and NDUFV2, both at the level of mRNA and protein." (PMID 17786189, 2007). "The duplications not currently classified as pathogenic or a VUS in the schizophrenia-LIQ individuals overlapped several interesting neuropsychiatric candidate genes, such as CNTN4, NDUFV2, and RCAN1." (PMID 29187259, 2017). "Furthermore, the mRNA level of NDUFV2 was positively correlated with BPRS and SAPS scores in the present study’s first-episode schizophrenia patients." (PMID 25713723, 2014). "The present study aimed to investigate the relationship between the clinical features of schizophrenia, and mitochondrial complex activation, based on measurement of mRNA levels in the NDUFV1, NDUFV2, NDUFS1, and UQCR10 genes involved in the peripheral mitochondrial complex." (PMID 25713723, 2014). "Focusing on the mitochondrial oxidative phosphorylation system (OXPHOS) in schizophrenia, revealed alterations in the enzymatic activities of complexes IV, II and I–III and in mRNA and protein levels of complex I subunits, NDUFV1 and NDUFV2, in post-mortem brain specimens." (PMID 18989376, 2008). "Previously, we have shown that in schizophrenia the mRNA and protein expression of the NDUFV1 and NDUFV2 were increased in platelets and lymphocytes as well as in the ventral parieto-occipital cortex, while reduced in the prefrontal cortex as compared with healthy subjects." (PMID 17786189, 2007). "Mithramycin induced a time dependent decrease in mRNA and protein levels of complex I subunits NDUFV1, NDUFV2 and NDUFS1, as well as of reelin, which was arbitrarily chosen as a gene known to be modulated by Sp1 and repeatedly reported to be abnormally expressed in schizophrenia." (PMID 17786189, 2007).
bipolar disorder (15 papers, 2008 to 2024). A disorder of the brain that causes unusual shifts in mood, energy, activity levels and the ability to carry out day-to-day tasks. "NDUFV2 encodes a 24-kDa subunit of the NDUFV2 protein of Complex I. Initial studies have suggested a possible link between the mRNA level of NDUFV2 and the state of bipolar disorder (BD)." (PMID 37168668, 2023). "NDUFV2 has been implicated in Alzheimer's disease, bipolar disorder, Parkinson's disease, and other pathologies." (PMID 32025618, 2020). "For example, it was suggested that polymorphisms of the NDUFV2 gene may be one of the genetic risk factors for bipolar disorder." (PMID 35471675, 2022). "NDUFV2 was upregulated in bipolar disorder but downregulated in ketosis, whereas CYCS and SDHAF3 were downregulated in bipolar disorder but upregulated in ketosis." (PMID 39125835, 2024). "The present findings of altered POLG, OGG1 and NDUFV2 expression point to disturbances within mitochondrial function and DNA repair mechanisms in bipolar disorder." (PMID 26241352, 2015). "In patients with bipolar disorder, upregulation of NDUFV2 was observed in a depressed state compared with a euthymic state." (PMID 26241352, 2015). "Moreover, the expression levels of NADH:Ubiquinone oxidoreductase core subunit v2 (NDUFV2), a mitochondrial complex I subunit gene, were decreased in lymphoblastoid cell lines derived from patients with bipolar disorder." (PMID 30285728, 2018). "Several lines of evidence implicate NDUFV2 in bipolar disorder." (PMID 26241352, 2015). "NDUFV2 expression has not previously been described in PBMCs of bipolar disorder patients and state-related alterations of NDUFV2 specifically have not been investigated." (PMID 26241352, 2015). "In addition, we demonstrated aberrant regulation of the POLG, NDUFV2 and, for the first time, the OGG1 gene, pointing to disturbances within mitochondrial function and DNA damage repair mechanisms as pathophysiological mechanisms in bipolar disorder." (PMID 26241352, 2015). "In bipolar disorder a reduction in the expression level of mitochondrial genes, including those of the OXPHOS was observed in hippocampal and prefrontal postmortem specimens, while an increase in complex I subunits NDUFV1 and NDUFV2 was observed in the parieto-occipital cortex." (PMID 18989376, 2008).
Parkinson disease (11 papers, 2008 to 2023). A progressive degenerative disorder of the central nervous system characterized by loss of dopamine producing neurons in the substantia nigra and the presence of Lewy bodies in the substantia nigra and locus coeruleus. "Further, mutations in the NDUFV2 gene producing the transcript ENST00000400033 have been associated with Parkinson's and Leigh syndrome." (PMID 34469537, 2021). "NADH dehydrogenase ubiquinone flavoprotein 2 (Ndufv2) is a subunit of mitochondrial complex I and polymorphisms of this are thought to be causative for Parkinson disease." (PMID 23738220, 2013). "The human homolog of CG5703, NDUFV2, has been linked to Parkinson's disease." (PMID 22715409, 2012). "The detected proteins are involved in a wide range of diseases; spastic paraplegia (HSPD1), cancer (BAX, PHB), optic atrophy (OPA1), ethylmalonic encephalopathy (ETHE1) and Parkinson's disease (NDUFV2)." (PMID 19476632, 2009). "For example, by searching mouseNET with a set of genes (Mapt, Sncaip, Tbp, Drd4, Ndufv2 and Nr4a2) already known to be involved in Parkinson's disease, we are able to extract other genes annotated to this disease and some novel candidates." (PMID 18818725, 2008). "NDUFA9, NDUFV2, and NDUFS3 are considered critical genes in oxidative phosphorylation and Parkinson’s disease, Huntington’s disease, and AD pathways." (PMID 35990086, 2022). "The K209R substitution in NDUFV2, reported in Parkinson's disease patients, did not significantly affect the enzyme activity or assembly." (PMID 32025618, 2020).
cardiomyopathy (7 papers, 2015 to 2025). A disease of the heart muscle or myocardium proper. "From a clinical perspective, the phenotype is still a relevant factor and can suggest a molecular diagnosis, such as NDUFV2 mutations identified in two siblings of our cohort displaying encephalopathy and cardiomyopathy." (PMID 39410537, 2024). "The deletion in patient 2 overlaps 24 known genes; only 1 has a disease-associated OMIM entry, NDUFV2, involved in autosomal recessive mitochondrial complex I deficiency characterized by early-onset cardiomyopathy and encephalopathy." (PMID 25844147, 2015). "Specific components of NADH‐ubiquinone oxidoreductase (Nduf) were upregulated, including core subunit V2 (Ndufv2), which is known to protect against doxorubicin‐induced mitochondrial dysfunction‐driven cardiomyopathy." (PMID 40468964, 2025). "NADH‐ubiquinone oxidoreductase subunits, especially subunit V2 (Ndufv2), were upregulated as previously shown in the context of doxorubicin treatment to protect against cardiomyopathy." (PMID 40468964, 2025). "PHB2 has been shown to ameliorate DOX-induced cardiomyopathy by inhibiting interstitial fibrosis and restoring the mitochondrial complex I function by interacting with NDUFV2." (PMID 39507806, 2024).
hypertrophic cardiomyopathy (7 papers, 2011 to 2024). A condition in which the myocardium is hypertrophied without an obvious cause. "P31 displayed, with homozygous mutation, c.120+5_120+8delGT in NDUFV2, a classic NDUFV2 phenotype represented by hypertrophic cardiomyopathy and encephalopathy, alongside with a rare skin condition." (PMID 37628588, 2023). "Since this mutation in NDUFV2 is known to cause hypertrophic cardiomyopathy, monitoring for this type of defect in heart muscle would be included as a medical management change." (PMID 29554876, 2018). "In a recent report, a 4-bp deletion in intron 2 (IVS2+5_+8delGTAA) in the NDUFV2 gene has been shown to associate with patients with early-onset hypertrophic cardiomyopathy and encephalopathy." (PMID 21548921, 2011). "The aim of this study is to examine the mitochondrial targeting of NDUFV2 and dissect the pathogenetic mechanism of one human deletion mutation present in patients with early-onset hypertrophic cardiomyopathy and encephalopathy." (PMID 21548921, 2011). "These examples support our argument that the mislocalization of NDUFV2 caused by the IVS2+5_+8delGTAA mutation in NDUFV2 gene is associated with early-onset hypertrophic cardiomyopathy and encephalopathy." (PMID 21548921, 2011). "Indeed, gene silencing of NDUFS3 and mutations in the NDUFV2 gene have been shown to lead to mitochondrial dysfunction, hypertrophic cardiomyopathy, and Leigh’s Syndrome." (PMID 25216282, 2014). "In clinical studies, a connection has been established between hypertrophic cardiomyopathy and mutations found in the NDUFS2 and NDUFV2 genes in patients undergoing clinic‐treatment." (PMID 38546629, 2024). "The NDUFV2 gene has been mainly studied in mental diseases, brain diseases, prostate cancer and hypertrophic cardiomyopathy." (PMID 36309697, 2022). "The patients of early-onset hypertrophic cardiomyopathy and encephalopathy were shown to have a homozygous mutation, a 4-bp deletion in intron 2 (IVS2+5_+8delGTAA), in NDUFV2 gene." (PMID 21548921, 2011). "The results of human disease cell model established that the impairment of mitochondrial localization of NDUFV2 as a mechanistic basis for early-onset hypertrophic cardiomyopathy and encephalopathy." (PMID 21548921, 2011). "The results of human disease cell model establish that the impairment of mitochondrial localization of NDUFV2 as a mechanistic basis for early-onset hypertrophic cardiomyopathy and encephalopathy." (PMID 21548921, 2011). "According to the original finding, fibroblasts from patients suffering from early-onset hypertrophic cardiomyopathy and encephalopathy had a significant reduction in the quality of NDUFV2 protein in mitochondria." (PMID 21548921, 2011). "Previous data from clinical researches indicated that the patients suffering from early-onset hypertrophic cardiomyopathy and encephalopathy disease frequently contain a 4-bp deletion in the NDUFV2 gene and produce a shortened NDUFV2 protein that lacks 19-40 residues." (PMID 21548921, 2011).
Encephalopathy (6 papers, 2011 to 2024). Encephalopathy is a term that means brain disease, damage, or malfunction. "Although NDUFV2 defects have also been reported in association with Leigh syndrome, our patient exclusively expressed symptoms of white matter degeneration (encephalopathy)." (PMID 30369941, 2018).
prostate carcinoma (3 papers, 2021 to 2025). A carcinoma that arises from epithelial cells of the prostate gland. "Mitochondrial-related genes including NDUFA10 and NDUFV2 participate in androgen regulation and may be candidate prognostic markers, which could be therapeutic targets of prostate cancer." (PMID 34124242, 2021). "In addition, NDUFV2 is involved in the regulation of androgens, which may be a prognostic marker and therapeutic target for prostate cancer." (PMID 41364140, 2025).
sleep disorder (3 papers, 2022 to 2025). A change from the patient's baseline sleeping pattern, in the hours slept and/or an alteration/dysfunction in the stages of sleep. "ATP5B, COX5A, GAPDH NDUFV2, SOD1, UQCRC1, and UQCRC2 have been reported as sleep deprivation and sleep disorder-related genes, and these studies have contributed to the development of candidate biomarkers for the diagnosis and treatment of plateau-induced sleep disorders." (PMID 36860517, 2023).
Parkinson's (2 papers, 2020 to 2021). "Indeed, NDUFV2, down-regulated in AD patients, has been addressed as a genetic variation promoting a mild form of Parkinsonism with a prognosis similar to that of idiopathic PD." (PMID 33327559, 2020).